PDPK1 (3-phosphoinositide dependent protein kinase 1)
Diseases named in the same sentence as PDPK1 in open-access papers (continued):
Sharing a sentence is not in itself a finding about the gene and the disease.
neuroblastoma (1 paper, 2024). Neuroblastoma (NB) is the most common solid, extracranial childhood tumor. "Using RNA-seq analysis, we identify the genes regulated by N-MYC and PDPK1 in multiple engineered CHP-134 neuroblastoma cell lines and compare them to previously published gene expression data collected in CHP-134 cells following inhibition of WDR5." (PMID 38605297, 2024). "In both these cell lines, the interaction of WDR5 with PDPK1 is inhibited by the R3A mutation with a concomitant decrease in N-MYC binding, indicating that across multiple N-MYC amplified neuroblastoma cell lines N-MYC can associate with PDPK1 through their shared direct interactions with WDR5." (PMID 38605297, 2024). "To understand the influence of PDPK1 on the transcriptome in N-MYC amplified neuroblastoma cells, we engineered CHP-134 cells so that endogenous PDPK1 is expressed in-frame with a FKBP12(F36V)-2xHA tag, allowing PDPK1 to be degraded by the dTAG method." (PMID 38605297, 2024). "In this study, we focus on the intersection of N-MYC with two cellular regulators that have known ties to cell cycle processes—PDPK1 and WDR5—to understand how each contributes to mitotic gene regulation in neuroblastoma cells marked by overexpression of N-MYC." (PMID 38605297, 2024). "Using a variety of genetically engineered N-MYC amplified neuroblastoma cell lines, we identified a small group of genes highly enriched within functional gene categories related to mitotic processes that are commonly regulated by N-MYC, WDR5, and PDPK1." (PMID 38605297, 2024). "Based on our data, depletion of PDPK1 in CHP-134 cells does not impact steady-state protein levels of N-MYC as has been seen for shRNA-mediated knockdown or chemical inhibition of PLK1 in neuroblastoma cells." (PMID 38605297, 2024). "Therefore, to characterize the influence of WDR5 and PDPK1 on mitotic gene expression in cells with high MYC levels, we performed a comparative transcriptomic analysis in neuroblastoma cell lines defined by MYCN-amplification, which results in high cellular levels of the N-MYC protein." (PMID 38605297, 2024).
osteoporosis (1 paper, 2025). A condition of reduced bone mass, with decreased cortical thickness and a decrease in the number and size of the trabeculae of cancellous bone (but normal chemical composition), resulting in increased fracture incidence. "Previous studies demonstrated that PDPK1 deficiency in osteoclasts protects OVX mice from developing osteoporosis." (PMID 39791175, 2025). "This study identified PDPK1, MAP1LC3B, ZFP36, DRAM1, and MPO as potential biomarkers and proposes a nomogram based on hub genes for predicting osteoporosis risk." (PMID 39791175, 2025).
pancreatic ductal adenocarcinoma (1 paper, 2021). An infiltrating adenocarcinoma that arises from the epithelial cells of the pancreas. "Eser and colleagues showed that hat PDPK1 is an essential effector of Kras, and that an intact PDPK1/PI3K axis is an essential tumor initiating event in cooperation with KRAS for increased cell plasticity, acinar-to-ductal metaplasia (ADM), and pancreatic ductal adenocarcinoma (PDAC) formation." (PMID 34079928, 2021).
prion disease (1 paper, 2021). A transmissible disease that is caused by a protein that is able to induce abnormal folding of normal cellular proteins, leading to characteristic spongiform brain changes, which are associated with neuronal loss without an inflammatory response. "The final study in this section looks at the enzyme 3-Phosphoinositide-dependent protein kinase-1 (PDK1), both in AD and prion disease." (PMID 34489620, 2021).
renal fibrosis (1 paper, 2020). A final common manifestation of a wide variety of chronic kidney diseases characterized by glomerulosclerosis and tubulointerstitial fibrosis. "An in vivo study also demonstrated that NDK mixture can inhibit the expression of PDPK1 by upregulating the expression of mir-129-5p and then inhibiting the PI3K/AKT pathway to improve renal fibrosis." (PMID 32454849, 2020). "Furthermore, NDK mixture can inhibit the expression of PDPK1 by upregulating the expression of mir-129-5p and then inhibiting the PI3K/AKT pathway to improve renal fibrosis." (PMID 32454849, 2020). "In summary, miR-129-5p functions to inhibit renal fibrosis and EMT in HK-2 cells via PDPK1." (PMID 32454849, 2020). "In conclusion, we further demonstrated in vivo that NDK mixture could inhibit the expression of PDPK1 by upregulating the expression of mir-129-5p and then inhibiting the PI3K/AKT pathway to improve renal fibrosis." (PMID 32454849, 2020).
serous ovarian cancer (1 paper, 2012). "Notably, the kinase PDPK1 is in the PI3K signaling pathway involved in serous ovarian cancer." (PMID 22403726, 2012).
Stroke (1 paper, 2022). Sudden impairment of blood flow to a part of the brain due to occlusion or rupture of an artery to the brain. "The toxic effects of CD8+T cells can be achieved through the FASL-PDPK1 pathway and inhibition of PDPK1 can effectively improve neural function after stroke." (PMID 36438975, 2022).
type 2 diabetes (1 paper, 2017). "miR-375 plays a role in the development and maintenance of the α- and β-cell mass in the normal pancreas and is upregulated in patients with type 2 diabetes.miR-375 targets 3-phosphoinositide-dependent protein kinase-1 (PDK1) in PC and inhibits PC cell proliferation in vitro." (PMID 28239461, 2017).
urothelial carcinoma (1 paper, 2017). A malignant neoplasm derived from the transitional epithelium of the urinary tract (urinary bladder, ureter, urethra, or renal pelvis). "The regulation of S6K by 3-phosphoinositide dependent protein kinase-1 (PDK-1) may explain the difference in inhibition of p-mTOR and p-S6 status as demonstrated after rapamycin treatment in urothelial carcinoma." (PMID 29100343, 2017).
tumor (65 papers, 2010 to 2026). "For instance, it was reported that human cancers with PIK3CA mutations where AKT activity is deficient, SGK3 serves as the main PDPK1 effector to drive tumour cells survival." (PMID 32926495, 2020). "Celecoxib and its derivatives are known to inhibit 3-phosphoinositide-dependent protein kinase 1, which is implicated in tumor invasion, angiogenesis and tumor progression." (PMID 25428375, 2015). "Furthermore, we investigated the relationship between this model and TME, and the results indicated that CPEB1, NOTCH3, NUAK1, and PDPK1 were strongly associated with the expression of tumor checkpoints and tumor immune infiltration." (PMID 36072578, 2022). "In short-term survivors of GBM (≤6 months), high levels of FABP5 protein were expressed, which was associated with highly proliferating tumor cells and the activation of the v-akt murine thymoma viral oncogene homolog and 3-phosphoinositide-dependent protein kinase-1." (PMID 32214002, 2020). "The polarized M2 macrophages can increase phosphoglycerate kinase 1 (PGK1) phosphorylation in tumor cells, mediated by 3-adenosine phosphate-dependent protein kinase 1 (PDPK1) in tumor cells by secreting IL-6." (PMID 40297580, 2025). "Here we found that they also exhibit higher phosphorylation levels of several kinases and TFs, which were previously associated with macrophages that promote tumor growth, such as MAFB, HSF1, PKACα, and PDPK1." (PMID 41255709, 2025). "BC cell lines with mutations in the helical domain (Exon 9) have shown dependency on the 3-phosphoinositide-dependent-protein kinase 1 (PDK1) target for tumor growth." (PMID 39444377, 2024). "As a result, we found that circ_0000376 silencing repressed NSCLC cell tumor properties by the miR-545-3p/PDPK1 axis." (PMID 36820067, 2023). "M2 macrophages secrete a large amount of IL-6, which subsequently enhances 3-phosphoinositide-dependent protein kinase 1 (PDPK1)-mediated phosphoglycerate kinase 1 (PGK1) threonine (T) 243 phosphorylation in tumor cells." (PMID 37012233, 2023). "M2 macrophages have shown to secrete interleukin-6 (IL-6), promoting the phosphorylation of Phosphoglycerate Kinase 1 (PGK1) in tumor cells mediated by 3-phosphoinositide-dependent protein kinase 1 (PDPK1)." (PMID 37298093, 2023). "Zhang and colleagues have demonstrated that M2 macrophages enhance 3-phosphoinositide-dependent protein kinase 1 (PDPK1)-mediated phosphoglycerate kinase 1 (PGK1) threonine (T) 243 phosphorylation in tumour cells by secreting IL-6." (PMID 37491279, 2023). "Copy-number analysis revealed that PDPK1 amplification was the only potentially tumor-related gene in the oncocytic cancer cell specimens." (PMID 35392240, 2022). "The subcutaneous xenograft models further confirmed that POU2F2 promoted tumor growth in a PDPK1 dependent manner." (PMID 33931589, 2021). "Neutralization of macrophage-derived IL-6 or inhibition of PGK1 T243 phosphorylation or PDPK1 in tumor cells markedly abrogates macrophage-promoted glycolysis, proliferation, and tumorigenesis." (PMID 33505964, 2020). "While down-regulation of genes such as CYP4A11, PLA2G4A, PLA2G3, LTC4S, CYP27A1, HMGCS2 and PDPK1 reduced patient overall survival time in most tumor types." (PMID 31074374, 2019). "Status of PDPK1 expression was established in 170 tumor samples with the following distribution: 9% −, 21% +, 52% ++, and 18% +++." (PMID 24500884, 2014). "Similarly, TAM-derived IL-6 can facilitate PDPK1-mediated glycolysis in GBM cells to promote tumor growth." (PMID 40626360, 2025). "Macrophages affected by lactic acid can also secrete IL-6, increasing 3-phosphoinositide dependent protein kinase 1 (PDPK1)-dependent phosphoglycerate kinase (PGK1) phosphorylation by inducing PDPK1 in tumour cells, resulting in enhanced glycolysis and tumourigenesis." (PMID 37108242, 2023).
tumor (continued). "In addition, in vivo assay related to the effects of miR-545-3p depletion, circ_0000376 overexpression, or PDPK1 depletion on tumor growth can further validate the regulatory effects of the circ_0000376/miR-545-3p/PDPK1 axis on NSCLC cell phenotypes." (PMID 36820067, 2023). "Collectively, circ_0000376 regulated NSCLC cell tumor properties by the miR-545-3p/PDPK1 pathway." (PMID 36820067, 2023). "Collectively, circ_0000376 regulated NSCLC cell tumor properties by the miR-545-3p/PDPK1 axis, suggesting that circ_0000376 could be employed as a therapeutic target for NSCLC." (PMID 36820067, 2023). "A recent study identified the locus containing PDPK1 gene (16p13.3) is more frequently amplified in lymph node metastases and CRPC, compared to primary tumours, suggesting PDPK1 may also support cancer metastasis." (PMID 32926495, 2020). "Furthermore, in other tumor models, the proliferation and progression of cells can be reduced by knockdown of PDPK1." (PMID 33384993, 2020). "Taken together, these results indicate that gga-miR-148a-5p can inhibit the proliferation and cycle of ALV-J-infected CEF cells by targeting PDPK1, indicating that gga-miR-148a-5p is a potential interfering target that can improve the host's infection of virus and tumor formation." (PMID 33384993, 2020). "Recent studies have shown that the locus containing PDPK1 gene (16p13.3) is more frequently amplified in lymph node metastases and castration‐resistant PCa, compared to primary tumours, we decided to focus on understanding the mechanism underlying PDPK1 mediated cell survival in PCa cells." (PMID 32926495, 2020). "We used A549‐Luc and A549‐PDPK1 (+/+)‐Luc cells to examine whether overexpression of PDPK1 resisted the effect of SM on tumour growth in vivo." (PMID 31475459, 2019). "Significantly reduced PDPK1 levels were seen in the tumor specimens with a ≥ 5-fold reduction of the number of cases staining 2+ and a concomitant increase in the number of cases who lost PDPK1 or stained weakly positive in the tumors (Wilcoxon matched-pairs signed rank test; p < 0.0001)." (PMID 30064387, 2018). "Such a hypothesis appears to be in line with the decreased PDPK1 expression levels in the tumor vs matched clinical specimens on tissue microarray staining." (PMID 30064387, 2018). "In addition, polarized M2 macrophages produce IL-6 to promote the phosphorylation of the threonine 243 of phosphoglycerate kinase 1 (PGK1T243) mediated by 3-phosphoinositide-dependent protein kinase 1 (PDPK1) in tumor cells, promoting glycolysis and tumor progression." (PMID 35062950, 2022). "However, in line with our data is a former in vivo study reporting that an inducible PDPK1 KD of 90% efficiency failed to suppress tumor formation in three different mouse models of PTEN-deficient cancer." (PMID 33785835, 2021). "All of these findings showed that PDPK1 may be a tumor suppressor." (PMID 33384993, 2020). "Furthermore, TAM-derived IL-6 induces the phosphorylation of PDPK1-mediated PGK1 threonine (T) 243 in tumor cells, to facilitate a PGK1-catalyzed reaction toward glycolysis by altering substrate affinity, which upholds PDAC initiation in a metabolic regulation way." (PMID 33505964, 2020). "However, whether PDPK1 has tumor suppressive or carcinogenic effects in tumors and cancers is still controversial." (PMID 33384993, 2020). "Among them, the expression of TIPRAP, WSCD1, TCP11L2, DPP4, CAB39 and PDPK1 were down-regulated, while PARP1, DEPDC1B, CKAP2, ORMDL2, MRPL44, POLD4 and TMEM187 were increased in tumor group." (PMID 39949782, 2025). "The effect of PDPK1 and autophagy inhibitor chloroquine in RCC in vivo was examined in a mouse tumor-bearing model." (PMID 38356720, 2024). "The overexpression of both PDPK1 and VASP was positively correlated with maximal tumor size and higher TNM stage." (PMID 32206125, 2020).
tumor (continued). "Expression patterns of PDPK1, one of the upregulated targets in LRCC, was studied in patients’ tumor samples and correlated with pathological variables and clinical outcome." (PMID 30064387, 2018). "Nevertheless, animal studies showed that mice with only 10% of the PDPK1 function exhibited a normal phenotype and when crossed with PTEN+/− mice, tumour formation capacity was disrupted." (PMID 29064423, 2017). "As an inhibitor of the 3-phosphoinositide dependent protein kinase 1 (PDPK1)–4 family, DCA reportedly inhibits tumor proliferation by reversing the bio-energetic profile of cancer cells." (PMID 27582548, 2016). "2-O-Bn-InsP5 specifically inhibits 3-phosphoinositide-dependent protein kinase 1 (PDK1) in vitro (IC50 in the low nanomolar range) and the PDK1-dependent phosphorylation of Akt in cell lines and excised tumours." (PMID 20051961, 2010). "Additionally, in LUAD, TCP11L2 was the only protein decreased in the tumor samples, and in LUSC, CAB39, DEPDC1B, DPP4, PDPK1, and POLD4 were significantly down-regulated." (PMID 39949782, 2025). "The present work analyzed the effects of circ_0000376 on NSCLC cell tumor properties and explored whether circ_0000376 participated in NSCLC development through the miR-545-3p-dependent PDPK1." (PMID 36820067, 2023). "PDPK1 is highly expressed in GBM and play important roles in cell growth and tumor development." (PMID 33931589, 2021). "Finally PDPK1 and ZEB1/2 members drive tumor metastasis spread via regulating epithelial–mesenchymal transition (EMT) during hypoxia." (PMID 34924998, 2021). "Importantly, PDPK1 inhibitors (GSK2334470 and BX‐795) significantly reduced tumour‐specific cell growth and synergized docetaxel sensitivity in PCa cells." (PMID 32926495, 2020). "We showed that knock‐down of endogenous human PDPK1 induced significant tumour‐specific cell death in PCa cells (DU145 and PC3) but not in the normal prostate epithelial cells (RWPE‐1)." (PMID 32926495, 2020). "This patient’s tumor cells also carried an amplification in each CTC of the 11q13.3 locus containing Cyclin D1 gene (CCND1), as well as gains of NOTCH3 (19p13.2), HTERT (5p15.33), and PDPK1 (16p13.3)." (PMID 31481116, 2019). "In an effort to explore the anti-tumor effects of ciglitazone on potential targets, we turned our attention to 3-phosphoinositide-dependent protein kinase 1 (PDK1), a master regulator of signal cascades that is involved in suppression of apoptosis and promotion of tumor growth including lung cancer." (PMID 24925061, 2014). "Of notice, study patients demonstrating high tumor PI3K-mediated signaling activity, as all array substrates of this specific pathway (PIK3R1, CTTN1, PLCG1, PDPK1, and RASA1) were highly phosphorylated, had particularly poor metastasis-free survival after radical treatment of the pelvic cavity." (PMID 23226389, 2012). "In A549 cells, TMEM116 knockdown downregulates PDPK1 (3-phosphoinositide-dependent protein kinase 1; historically referred to as PDK1) and suppresses proliferation, clonogenicity, invasion, and migration in vitro, as well as metastatic burden and subcutaneous tumor growth in vivo." (PMID 41596760, 2026). "A combination of genetic and chemical genetic experiments demonstrate that these defects are due to the loss of the lipid phosphatase activity of PTEN and to the activation of 3-phosphoinositide-dependent protein kinase-1 (PDPK1 (PDK1)), but do not depend on the AKT-mTOR tumor suppressor pathway." (PMID 26809587, 2016).